IDH1 (isocitrate dehydrogenase (NADP(+)) 1)
Diseases named in the same sentence as IDH1 in open-access papers (continued):
Sharing a sentence is not in itself a finding about the gene and the disease.
acute myeloid leukemia (continued). "In acute myeloid leukemia (AML), IDH2 mutations are more prevalent than IDH1 mutations and usually affect codon R140." (PMID 34997121, 2022). "For example, in acute myeloid leukemia (AML), an association between SNHG7 and SNHG12 lncRNAs and specific clinical/molecular features, including white blood cell (WBC) counts and mutations in IDH1, RUNX1, and NPM1 genes, shows high value of SNHG7 in correlation with extensive features." (PMID 35111760, 2021). "IDH1 and IDH2 mutations are found in multiple tumors, including glioma and acute myeloid leukemia (AML)." (PMID 35008250, 2021). "A number of malignancies have been found to be associated with mutations in the gene encoding isocitrate dehydrogenase 1 (IDH1) and IDH2, including acute myeloid leukemia (AML) and myeloproliferative neoplasms." (PMID 34360786, 2021). "Enasidenib and Ivosidenib, inhibitors for isocitrate dehydrogenase 1 and 2 (IDH1/2), were approved for treating relapsed or refractory acute myeloid leukemia (AML) in 2017 and 2018, respectively." (PMID 34930302, 2021). "IDH1 mutations involving codon 132 and IDH2 mutations involving codons 140 and 172 occur in a variety of human cancers, including acute myeloid leukemia (AML), diffuse gliomas, cholangiocarcinoma, and chondrosarcoma." (PMID 32333643, 2020). "Acquired somatic mutations in the isocitrate dehydrogenase 1 and 2 genes (IDH1 and IDH2), have been reported in acute myeloid leukemia (AML), myelodysplastic syndromes (MDS), and chronic myeloproliferative neoplasms (MPN)." (PMID 32629801, 2020). "Regarding the MPN/AML transformation, mutations in genes encoding epigenetics modifiers such as ASXL1, IDH1, IDH2, EZH2, and TET2 are associated with nearly 30% of secondary leukemia transformations and de novo acute myeloid leukemia." (PMID 29515972, 2018). "In acute myeloid leukemia (AML), mutations in DNA methylation regulators such as DNMT3A, TET2, IDH1 and IDH2 are frequent, and loss of function of TET2 and DNMT3A are early events in leukemogenesis." (PMID 26829670, 2016). "Mutations of isocitrate dehydrogenase 1 (IDH1) and IDH2 in acute myeloid leukemia (AML) cells produce the oncometabolite R-2-hydroxyglutarate (R-2HG) to induce epigenetic alteration and block hematopoietic differentiation." (PMID 27577048, 2016). "The scientific community was further encouraged to consider this abnormality when another cancer genome project also reported the very same mutation in IDH1 and IDH2 of acute myeloid leukemia (AML) patients." (PMID 25502799, 2014). "Acute myeloid leukemia (AML) with a normal karyotype (CN-AML), which accounts for 40–50% of AML cases, commonly presents with genetic mutations in ASXL1, MLL, DNMT3A, TET2, IDH1 and IDH2 genes, all of which have important roles in epigenetic regulation." (PMID 24202321, 2013). "At the same time, other genetic alterations commonly found in acute myeloid leukemia, like DNMT3, TET2, NPM1, IDH1 or IDH2, are rarely detected, confirming the unique pathogenesis of APL." (PMID 38921185, 2024). "To date, IDH1 and IDH2 inhibitors have been approved in acute myeloid leukemia and more recently in cholangiocarcinoma; nevertheless some clinical trials for other solid tumors with evidence of IDH1/2 mutations, including mCRC, are ongoing." (PMID 37064137, 2023). "Ivosidenib and enasidenib are targeted inhibitors of the IDH1 and IDH2 proteins, respectively, which have been confirmed to be efficient and tolerable in acute myeloid leukemia (AMLs) in previous studies." (PMID 35042566, 2022).
acute myeloid leukemia (continued). "Mutations in proto-oncogene IDH1 and IDH2, are usually found in glioma and acute myeloid leukemia (AML), resulting in a hypermethylated profile that confer a selective advantage to the mutated subpopulation of cells, in term of growth rate and stemness capability." (PMID 39086963, 2022). "The first-in-class IDH1 inhibitor is ivosidenib (AG-120), an oral small molecule, already approved by FDA for patients with IDH-mutant acute myeloid leukemia." (PMID 36045702, 2021). "Allosteric inhibitors of mutant IDH1 or IDH2 induce terminal differentiation of the mutant leukemic blasts and provide durable clinical responses in approximately 40% of acute myeloid leukemia (AML) patients with the mutations." (PMID 33972549, 2021). "Ivosidenib, a mutant IDH1 inhibitor, and enasidenib, a mutant IDH2 inhibitor, have been approved for treatment of relapsed/refractory acute myeloid leukemia (AML)." (PMID 33322351, 2020). "Selective IDH1 and IDH2 inhibitors have been approved for targeted therapy of acute myeloid leukemia." (PMID 32333643, 2020). "IDH1/2 mutations have also been found in several types of cancers, covering enchondroma, chondrosarcoma, angioimmunoblastic T cell lymphoma (AITL), intrahepatic cholangiocarcinoma (ICC), and acute myeloid leukemia (AML)." (PMID 31652645, 2019). "Recently, the IDH1 inhibitor enasidenib, and IDH2 inhibitor ivosidenib, were approved in the treatment of patients with acute myeloid leukemia (AML)." (PMID 31803611, 2019). "Breakthroughs in whole genome sequencing (WGS) of cancer were evident when recurrent mutations were found in the active site of the cytosolic NADP + −dependent isocitrate dehydrogenase 1 gene (IDH1), first identified in glioma and then in acute myeloid leukemia (AML)." (PMID 25411563, 2014). "In the last 3 years, alone mutations in the genes TET2, IDH1, IDH2, DNMT3a, and EZH2 have all been found in patients with myeloproliferative neoplasms (MPNs), myelodysplastic syndromes (MDSs), and/or acute myeloid leukemia (AML)." (PMID 21811504, 2012). "Further research is warranted to elucidate the genetic predispositions that may facilitate the transformation of leukemic MPNs into acute myeloid leukemia (AML), with emphasis on genes such as ASXL1, IDH1, IDH2, and SRSF2, among others." (PMID 39682300, 2024). "Recent research revealed that frequent hematologic and somatic cell variation of IDH1 have been related to certain cancers, including myelodysplastic syndromes (MDS), gliomas (grade II and III), acute myeloid leukemia (AML), intrahepatic cholangiocarcinoma, and some other sarcomas." (PMID 35402370, 2022). "Similar models recapitulate relevant mutations in Isocitrate dehydrogenase 1 and 2 (IDH1 and IDH2) mainly found in low-grade gliomas, secondary glioblastomas, and acute myeloid leukemia (AML), without the limitations of the earlier models." (PMID 36401282, 2022). "Multiple IDH1 and IDH2 inhibitors are reported, though only one IDH1 inhibitor (ivosidenib) and one IDH2 inhibitor (enasidenib) have been approved for clinical use, i.e. for acute myeloid leukaemia (AML) treatment where the cancer cells make an IDH variant." (PMID 35970853, 2022). "Mutations targeting genes encoding DNA methyltransferase (DNMT), TET family of DNA demethylases, and isocitrate dehydrogenase (IDH1, IDH2) that produce TET inhibitory metabolite, 2-hyoxyglutarate (2-HG), are found in more than half of acute myeloid leukemia (AML)." (PMID 34336831, 2021). "Interestingly, genetic alterations commonly found in acute myeloid leukemia like DNMT3, TET2, NPM1, IDH1 or IDH2 are rarely detected, suggesting that PML-RARA exhibits a distinct transformation pathway among AML." (PMID 32295268, 2020).
acute myeloid leukemia (continued). "The association between DNA methylation and IDH1 was not unique to GBM and it also occurred in acute myeloid leukemia (AML)." (PMID 31497535, 2019). "IDH1 and IDH2 mutations have been found in other non-CNS neoplasms, including cholangiocarcinoma, acute myeloid leukemia, chondrosarcoma, and angioimmunoblastic T-cell lymphoma, but the pathogenesis in these entities remains unclear." (PMID 40546613, 2025). "Mutations in isocitrate dehydrogenase (IDH), particularly in IDH1 and IDH2, have emerged as critical molecular events in various cancers, most notably gliomas, acute myeloid leukemia (AML), and chondrosarcomas." (PMID 40724998, 2025). "Therefore, IDH1 and IDH2 inhibitors (ivosidenib and enasidenib) would regulate both DNA and histone demethylation, and have been approved by the FDA for the treatment of relapsed or refractory acute myeloid leukemia (AML)." (PMID 38044445, 2023). "It is converted from α-KG by mutant isocitrate dehydrogenase (IDH1 and IDH2) that often occurs in glioma and acute myeloid leukemia (AML) patients." (PMID 36139121, 2022). "Previous research has established the role of IDH1 and/or IDH2 in mediating reductive carboxylation in acute myeloid leukemia (AML) cells." (PMID 35740646, 2022). "Mutations in the isocitrate dehydrogenase (IDH) family, notably IDH1 and IDH2, have been identified in several cancers such as grade II and III gliomas and acute myeloid leukemia (AML)." (PMID 34503108, 2021). "Recurrent mutations in IDH1 or IDH2 in acute myeloid leukemia (AML) are associated with increased DNA methylation, but the genome-wide patterns of this hypermethylation phenotype have not been comprehensively studied in AML samples." (PMID 34873300, 2022). "The function is not known, but IDH1 is an interesting region as there are several IDH targeted therapies underway, currently tested both in acute myeloid leukemia and in glioma." (PMID 31842352, 2019).
oligodendroglioma (372 papers, 2010 to 2026). A well-differentiated (WHO grade II), diffusely infiltrating neuroglial tumor, typically located in the cerebral hemispheres. "Oligodendroglioma is genetically defined by mutations in isocitrate dehydrogenase 1 or 2 (IDH1/IDH2) and 1p/19q codeletion." (PMID 41928812, 2026). "Oligodendrogliomas are characterized by IDH1/2 mutations in combination with complete 1p/19q codeletion, often with TERT promoter mutations and CIC/FUBP1 alterations, which results in a favorable prognosis and chemosensitivity." (PMID 41596318, 2026). "In the updated classification, oligodendrogliomas are defined by the presence of isocitrate dehydrogenase IDH1 or IDH2 mutations and 1p/19q co-deletion." (PMID 40143126, 2025). "The 2021 WHO classification of brain tumours defined oligodendrogliomas as genetically presenting an IDH1/2 mutation and the codelection of chromosome arms 1p and 19q." (PMID 40870498, 2025). "With the advancement in large-scale genome sequencing, additional important molecular alterations, such as mutations in the IDH1/2 genes, were identified in the majority of oligodendrogliomas." (PMID 40426960, 2025). "Glioblastomas are classified as those that are IDH wildtype, and astrocytomas and oligodendrogliomas have the IDH1 mutation, but oligodendrogliomas are further defined by a 1p19q chromosomal codeletion." (PMID 41002991, 2025). "Under the 2021 WHO classification, oligodendroglioma is defined exclusively by the presence of an IDH1 or IDH2 mutation together with whole-arm 1p/19q codeletion." (PMID 41375081, 2025). "Postoperative genetic testing confirmed the IDH1 R132H mutation, 1p/19q co-deletion, and pTERT mutation, resulting in a final diagnosis of oligodendroglioma, WHO CNS grade 2." (PMID 40994716, 2025). "In oligodendrogliomas, IDH1 gene mutations are strongly associated with dysfunctions of cellular cytosol and peroxisomes, while IDH2 mutations are only detectable in a small number of oligodendrogliomas that do not carry IDH1 mutations." (PMID 40426960, 2025). "Historically they were defined by histopathological features, but the 2021 WHO diagnostic criteria defined oligodendroglioma by molecular markers, specifically the co-occurrence of an IDH1 or IDH2 mutation and a 1p/19q codeletion." (PMID 41375081, 2025). "Oligodendrogliomas have long been associated with a more favorable prognosis, and are defined by the combined presence of IDH1/2 mutations and 1p/19q codeletion." (PMID 41346390, 2025). "For a confirmed oligodendroglioma diagnosis, testing for 1p/19q co-deletion along with IDH1 mutation is required, and hence, molecular information for both biomarkers is available." (PMID 39767640, 2024). "The liquid biopsy analysis obtained in this case study further proves the effectiveness of such alternative diagnostic methods in metastatic oligodendrogliomas via the detection of IDH1 c.395G > A; p.Arg132His gene mutation." (PMID 39061087, 2024). "Considering the T+/P+ group (n = 10), the highest number of patients with IDH1 mutations in cfDNA were found in the diffuse astrocytoma (40%), following the anaplastic astrocytoma (30%), oligodendroglioma (20%), and GBM (10%)." (PMID 38172718, 2024). "Oligodendroglioma is molecularly defined by the presence of the isocitrate dehydrogenase 1 (IDH1) (most commonly IDH1 p.R132H) or IDH2 mutations and 1p/19q codeletion, frequently with an additional Telomerase Reverse Transcriptase (TERT) promoter mutation." (PMID 39061087, 2024). "The diagnosis of oligodendroglioma requires the presence of IDH1/2 mutation combined with 1p/19q codeletion assessed through a FISH analysis and/or molecular sequencing." (PMID 39456545, 2024). "Incorporating mutations in the IDH1 gene within oligodendroglioma models represents the genetic milieu observed in human oligodendrogliomas." (PMID 38807869, 2024). "Pediatric oligodendroglioma typically lacks IDH1/2 mutations and 1p/19q co-deletion, making a differential diagnosis from DNET precarious." (PMID 36639714, 2023).
oligodendroglioma (continued). "Genetic mutations of the telomerase reverse transcriptase (TERT) promoter region do not co-exist with IDH1 mutations in primary GBMs; however, co-mutations in TERT promoter and IDH1/2 are often detected in oligodendrogliomas, which indicates a good prognosis." (PMID 37092846, 2023). "A similar result was obtained in an IDH1 R132H mutated patient-derived BT237 oligodendroglioma cell line." (PMID 38066546, 2023). "Nevertheless, a patient affected by IDH1 mutant oligodendroglioma recently showed reduced tumour-associated epilepsy after treatment with the IDH1 mutant inhibitor AG-120 (ivosidenib)." (PMID 37296846, 2023). "Oligodendroglioma is genetically defined as a tumor harboring a IDH1/IDH2 mutation involving the co-deletion of chromosome arms 1p and 19q." (PMID 35267650, 2022). "Of particular interest herein are the chromosomes 1p and 19q, which are co-deleted in the oligodendrogliomas with concurrent IDH1/IDH2 mutations." (PMID 36360312, 2022). "Studies utilising human oligodendroglioma cells have shown that the IDH1 R132 mutation leads to higher enzymatic activity than that brought about by IDH2 R172." (PMID 36042521, 2022). "It is acknowledged that the occurrence of the IDH1/2 mutation remains the upstream genetic event in two diffuse glioma lineages: diffuse astrocytomas and oligodendrogliomas." (PMID 35682718, 2022). "According to WHO 2021 brain tumor classification, we identified 14 patients with a molecular oligodendroglioma profile (IDH1 or 2 mutations, and 1p–19q chromosomal arm heterozygosity loss), of which 10 are WHO grade II and four WHO grade III." (PMID 36176387, 2022). "Histopathological evaluation revealed an oligodendroglioma, IDH1 mutated, 1p/19q-co-deleted WHO II, and a concomitant and adjuvant radiochemotherapy (50 Gy) with temozolomide (6 cycles) was initiated." (PMID 35018523, 2022). "For example, oligodendrogliomas were only diagnosed based on the presence of IDH1 mutation and 1p/19q codeletion." (PMID 34941573, 2022). "The diagnosis of oligodendroglioma requires the coexistence of IDH1/2 mutation and 1p/19q codeletion." (PMID 34165590, 2021). "We present here a rare case of multifocal high grade oligodendroglioma with supratentorial and infratentorial lesions, distinct IDH1 mutations, and differential response to PCV chemotherapy." (PMID 34587990, 2021). "In our dataset, only 71% of IDH1/2 mutated 1p19q codeleted samples were originally classified as oligodendrogliomas." (PMID 33778493, 2021). "Oligodendroglioma is characterised by either IDH1 or IDH2 mutations combined with the loss of both 1p/19q chromosomal arms." (PMID 33477674, 2021). "The role of IDH1 mutations in predicting response to chemotherapy for oligodendrogliomas has been difficult to establish, in contrast to the well-established predictive value of 1p/19q-codeletions in predicting sensitivity to PCV." (PMID 34587990, 2021). "Based on current WHO guidelines, the distinction between oligodendrogliomas and diffuse astrocytomas necessitates the detection of several molecular markers, primarily the IDH1/2 mutation status and whole arm 1p19q codeletion status." (PMID 33778493, 2021). "The oligodendrogliomas showed a high rate of IDH1 mutation, followed by anaplastic oligodendrogliomas and diffuse astrocytomas (all > 75%)." (PMID 35996504, 2021). "A total of 545 samples were classified as oligodendrogliomas, harboring IDH1/2 mutations and 1p19q codeletion." (PMID 33778493, 2021). "And most oligodendrogliomas with 1p/19q co-deleted, which indicates poor prognosis, are accompanied by IDH1 and IDH2 mutation." (PMID 34722274, 2021). "The TS603 subcutaneous xenograft model of oligodendroglioma (featuring pathognomonic codeletion of 1p/19q chromosome arms and mutation of IDH1) has been utilized to test the antitumor efficacy of the mutant IDH1 inhibitor AGI-5198." (PMID 33806933, 2021).